EGFR (epidermal growth factor receptor)
Diseases named in the same sentence as EGFR in open-access papers (continued):
Sharing a sentence is not in itself a finding about the gene and the disease.
cancer (continued). "The immunotoxin functions assessed in A431 cancer cells and EGFR‐negative HEK293 cells were found to have IC50 values of 22.4 ± 3 and >620.4 ± 5 nM, respectively." (PMID 35322728, 2022). "Here, we validated a comprehensive targeted cancer gene panel for simultaneous detection of SNVs and indels in 523 cancer-related genes, CNVs of 69 genes, gene fusions of 55 driver genes including exon skipping events in MET and EGFR, and the immunotherapy predictive markers MSI and TMB." (PMID 35626061, 2022). "Interactions between mucin 4 (MUC4) and the epidermal growth factor receptor (EGFR) are involved in carcinogenesis, and may lead to matrix metalloproteinase-9 (MMP9) overexpression, exacerbating cancer cell invasiveness." (PMID 36400876, 2022). "The genomic features that are linked to the responses of the two drugs are also biologically relevant; for example, EGFR is the upstream factor of PI3Ks, and the effectiveness of combined CDK4/6 (targets of CDKN2A) and PI3K inhibition has been shown in other cancer models." (PMID 35992090, 2022). "We have developed a bivalent HER2 aptamer-EGFR siRNA chimera that showed promise in mouse models by interfering with the function of HER2 and EGFR receptors and inducing apoptosis in HER2-expressing cancer cells." (PMID 35142964, 2022). "Moreover, the application of nanoparticle-conjugated epidermal growth factor receptor (EGFR) and HER2 receptors on different cancers leading to increased efficacy of different cancer drugs have recently been demonstrated." (PMID 35775004, 2022). "EGFR and HER-2 nanobodies demonstrated very efficient targeting in cancer therapy." (PMID 35892709, 2022). "The stress signals usually induce the noncanonical pathway of EGFR, and the stress signals can be easily observed in cancer cells providing survival and resistance to therapies." (PMID 36438839, 2022). "Our analysis of data from the METABRIC cohort demonstrated the expression of EGFR in 40% of basal subtype cancer patients; most of them did not co-express HER2." (PMID 35955836, 2022). "Taken together, considering that EGFR can establish a functional complex with TMEM16A, there may be an indirect relationship between the expression of TMEM16A and HPV + cancer." (PMID 35668455, 2022). "Mutations in MAATP53, EGFR, FAT4, KMT2C, ARID1A, FAT1, and RNF213 were observed in the original cancer tissues, whereas KRAS and BRAF mutations were not identified." (PMID 35721089, 2022). "It interacts with the EGFR, the PDGF, and the colony-stimulating factor (CSF) and might promote angiogenesis in cancer through the EGFR/VEGFA pathway and the metastasis of HPV-containing malignancies." (PMID 35163748, 2022). "Interestingly, there is evidence of a synergy between the EGFR (the most frequently activated RTK in our study) and ephrin receptors in cancer progression." (PMID 36230684, 2022). "For the study, the expression changes of EGFR, P-EGFR, ERK1/2 and P-ERK1/2, the related molecules in the EGFR-TK signal transduction pathway were measured to investigate the binding and regulatory relationship between 3l and EGFR in cancer cells." (PMID 36467103, 2022). "Moreover, human papillomavirus (HPV) infection can modulate TMEM16A expression along with epidermal growth factor receptor (EGFR), whose phosphorylation has been reported as a potential co-biomarker of HPV-positive cancers." (PMID 35668455, 2022). "EGFR-targeting nanobodies have been isolated by phage display, also in competition with other specific ligands (i.e., EGF or cetuximab), leading to the identification of several excellent scaffolds that have been used to target EGFR-overexpressing cancers." (PMID 35213974, 2022).
cancer (continued). "There are growing reports using nanobody-based immunotoxins to treat cancers by targeting a variety of antigens such as glypican-3, glypican-2, EGFR, HER2, VEGFR2, CD7 and CD38, which indicates the great potential of nanobody-based immunotoxins for cancer therapy." (PMID 36435809, 2022). "The enrichment of KEGG pathways demonstrated the target genes are mainly related to the pathway in cancer, the Phosphatidylinositol 3-kinase (PI3K)/Akt signaling pathway, and the epidermal growth factor receptor (EGFR) tyrosine kinase inhibitor resistance pathway." (PMID 35359572, 2022). "We have partitioned this multi-component review into different sections in which we summarized landmark research-works which highlighted betulinic acid mediated regulation of JAK/STAT, VEGF, EGF/EGFR, TRAIL/TRAIL-R, AKT/mTOR and ubiquitination pathways in the inhibition of cancer." (PMID 36615262, 2022). "Functional crosstalk between 5-HT7R and EGFR may also regulate EGFR internalization, and therefore, downstream signaling including MAPK cascade and known to be involved in cancer cell proliferation." (PMID 35455961, 2022). "Overexpressed membrane-bound mucins interact with receptor tyrosine kinases such as epidermal growth factor receptor (EGFR) and attenuate signalling pathways downstream of transforming growth factor-α (TGF-α) and EGFR and hence play protective roles for cancer cells." (PMID 35910854, 2022). "This trimeric complex plays critical roles in ligand-induced activation of several RTKs, including the EGFR, insulin receptor (IR), the nerve growth factor (NGF) TrkA receptor, and TOLL-like receptors (TLRs), all of which are upregulated in cancer." (PMID 35326525, 2022). "CIC was also identified as a determinant of sensitivity to blocking EGFR signaling in neural stem cells or NSCLC cell lines, suggesting that inactivation of CIC may counteract MAPK inhibition in human cancer." (PMID 36358827, 2022). "A large proportion of genetic mutations in cancer is comprised of single-nucleotide changes in genes like NOTCH, EGFR and KRAS." (PMID 35008996, 2022). "Overexpression of EGFR can lead to unregulated activation of its downstream signaling pathways, which include PI3K/AKT, Ras-ERK/MAP kinase, Src, JAK/STAT, and PKC, thereby leading to uncontrolled proliferation, survival, migration of invasion of cancer cells." (PMID 36313358, 2022). "Epidermal growth factor receptor (EGFR), as a receptor for epidermal growth factor (EGF) and transforming growth factor-α (TGF-α), has been found to facilitate the growth and aggressiveness of cancer cells." (PMID 34991599, 2022). "The cancer cell with this resistance can sustain oncogenic signaling with continuous inhibition of target molecules, such as EGFR and HER2 amplification upon MET exon 14 inhibition in non-small lung cancer (NSCLC)." (PMID 36140200, 2022). "Photosensitizer molecules, i.e., manganese phthalocyanine (MnPc), were loaded into the ferritin cavity, and the MnPc@7D12-Ftn particles were efficiently internalized by EGFR-overexpressing cancer cells, but not by EGFR-negative cells." (PMID 35213974, 2022). "DSF-102 showed different cytotoxic effects on human cancer lines: the viability of low expressing EGFR cells (i.e., A375) was not affected by up to 100 μM compound concentration." (PMID 35954311, 2022). "Moreover, EGFR, a pioneer member of the RTK family, is frequently overexpressed in human cancers, and its activation is crucial for essential cancer cell processes, including cell growth, survival, and drug resistance." (PMID 36158676, 2022). "An enhanced and specific uptake and an increased phototoxicity were observed for the mTHPC-loaded micelles decorated with the EGa1 nanobody as compared to non-targeted micelles on EGFR-overexpressing cancer cells." (PMID 35213974, 2022).
cancer (continued). "Nevertheless, our pre-clinical and human correlates suggest that EGFR-mutant cell sub-populations with high competence for brain metastasis and TKI resistance may be detected in pre-treatment cancers or tumors first growing outside of the CNS." (PMID 36509758, 2022). "Both EGFR and ALK targets are crucial for cancer proliferation." (PMID 35754819, 2022). "In contrast, the triple negative (HER2‐/ER‐/PR‐) MDA MB231 cells showed negligible fluorescent signal for HER2, ER, and PR, but were positive for cancer markers (EGFR (not shown) and MUC1 and EpCAM)." (PMID 35508767, 2022). "As pyruvate kinase M2 (PKM2) is the rate-limiting enzyme controlling the final step of glycolysis and serves as a major regulator of the Warburg effect in different cancer cells, the regulation of PKM2 by EGF, particularly in high EGFR–expressing cells, is thus of great importance." (PMID 35931120, 2022). "Very recently, Elbadawi reported 2-arylquinolines and 2,6-diarylquinoline derivatives as new dual EGFR/FAKIs to fight cancer by a non-overlapping downstream signalling/inhibition, as previously demonstrated by Ai." (PMID 35742823, 2022). "Studies have shown that GPER mediates nongenomic signal transduction of estrogen in a variety of estrogen-sensitive cancer cells by activating the nongenomic EGFR-dependent signaling pathway formed by PI3K/Akt." (PMID 36248433, 2022). "At the protein level, the expression levels of EGFR, HSP90AA1, and mTOR were significantly different between normal and cancer tissues (all p < 0.05)." (PMID 36569844, 2022). "Thus, combined inhibition of MEK and their upstream kinases (e.g., RAF, RAS, EGFR, etc.)are expected to enhance MAPK signaling inhibition and show better clinical efficacy than monotherapy in RAS mutant cancers, as did in clinical trials now." (PMID 35966590, 2022). "13/24 pairs showed discordant EGFR IHC results; in all these 13 patients, EGFR was positive (≥1+ membranous staining intensity found in at least 10% of the cancer cells) in the peritoneal, yet negative in the primary tissue samples." (PMID 35212471, 2022). "Since HER-2 is not expressed in TNBC diagnosis, the production of nanobodies for the diagnosis and treatment of cancer cells should be performed against other antigens expressed in TNBC such as TNF-α, EGFR, CD3, CTLA-4, STAT3, AKT2, GTP-binding protein Rho, CapG, fibronectin, and CA-IX." (PMID 35933373, 2022). "As a ligand of EGFR, the affinity of BTC to EGFR could affect cell growth and therapy resistance in various cancers." (PMID 35846125, 2022). "bsTCEs targeting EGFR-positive cancer cells for γδ T cell-mediated death have been developed and have demonstrated efficacy in killing CRC cells while sparing EGFR+ keratinocytes, suggesting that this treatment may have a high therapeutic index in patients." (PMID 35205776, 2022). "Src inhibitor dasatinib synergizes with trametinib to induce cell cycle arrest and apoptosis by downregulating TAZ in KRAS-mutant cancer cells, but not in wild type KRAS or EGFR mutant cancer cells." (PMID 35966590, 2022). "Importantly, BCAT1, EGFR and JAK2 are required for cell proliferation signaling in cancer cells or preadipocytes." (PMID 35269469, 2022). "2D5 peptide inhibited the proliferation of human, but not murine, cancer cells, suggesting that STAP-2 contributes to EGFR-mediated proliferation of human cancer cells, but not murine cancer cell lines." (PMID 36410436, 2022). "A growing body of evidence now demonstrates that asporin acts as an extracellular matrix component or intracellular protein that positively or negatively controls proliferation, invasion, and metastasis of cancer cells by regulating the TGF-β, EGFR, and CD44 signaling pathways." (PMID 35600399, 2022).
cancer (continued). "Numerous studies have shown that EGFR and its downstream signals are overactivated in various cancer cell lines, but not in normal cells, suggesting that 2D5 peptide with high sequence specificity is preferentially cytotoxic against EGFR-overactivated cells." (PMID 36410436, 2022). "In addition, using docking simulation studies, CHE has a high binding affinity for EGFR and DHFR, which are overexpressed in cancer cells." (PMID 35881165, 2022). "As MPZL3 and HER3 interact directly, it may be possible to identify cancers dependent on this interaction and the upstream activity of HER3-activating kinases, such as Met, EGFR and HER2, via this mechanism." (PMID 35249128, 2022). "Previous studies have reported increased activation of the EGFR/PI3K/AKT signal transduction pathway in EGFR-TKI-resistant NSCLC cells, and this activation promotes cell proliferation and suppresses the apoptosis of cancer cells." (PMID 35408854, 2022). "We first explored whether molecular-targeted drugs can select cancer cell clones harboring specific resistance gene alterations in cell line mixtures including EGFR-TKI-sensitive and EGFR-TKI-resistant cells." (PMID 35326664, 2022). "There were two common proteins (EGFR and ESR1) that had DIHCP features in all cancers studied." (PMID 36422095, 2022). "The active siRNA delivery of the DTPA-derivatized NM-scFv was evaluated in vitro with EGFR-overexpressing cancer cells and compared to non-derivatized NM-scFv." (PMID 36559172, 2022). "Pharmacological inhibitors of EGFR and NF-κB signaling pathways as well as modulation of ProT and HOTAIR expression may be further explored for ameliorating cachexia in cancer patients undergoing chemotherapy." (PMID 36471329, 2022). "Since the activation of EGFR signaling may be involved in cancer cell invasion, we carried out a transwell assay and found that ST3GAL6 knockdown could significantly increase cancer cell invasiveness." (PMID 36092699, 2022). "EGF/EGFR signaling triggered the release of EpEX from cell-surface EpCAM, after which the shed EpICD bound with EGFR to stabilize PD-L1 through the EGFR/ERK pathway in cancer cells." (PMID 36369033, 2022). "Secondly, we made the subgroup according to cancer molecular type, but the limited data from enrolled studies only supported the analyses based on COX-2, EGFR, and PEGM status, and we found EGFR wild-type patients obtain a prolonged PFS in celecoxib-combined palliative therapy." (PMID 36135051, 2022). "Some cell markers such as EGFR, PSMA, PSA, AR, CD133 (stem cell marker), and E-cadherin (EMT) have been used without a clear association to predict cancer outcomes." (PMID 35207452, 2022). "However, the majority of NSCLC patients eventually develop resistance to TKI, hence, the need to develop novel classes of drugs targeting EGFR for more efficacious long-term treatment of NSCLC and other types of cancer." (PMID 35235599, 2022). "EGFR, as a receptor tyrosine kinase (RTK), is a carcinogen and a therapeutic target for many cancers, which can activate many carcinogenic signal pathways in cancer cells." (PMID 36532716, 2022). "By leveraging the genomic biomarker data collected from consenting patients who participated in the Cancer and Leukemia Group B (CALGB)/SWOG 80405 trial and other relevant CRC datasets, here we investigate additional mechanisms of resistance to anti-EGFR and anti-VEGF containing therapies." (PMID 36117191, 2022). "There has yet to be any studies investigating the direct binding of TRPM7 and EGFR in cancer cells, nor is there any evidence of TRPM7 interacting with ANOs." (PMID 36497413, 2022). "MiR-193a, one of the candidate miRNAs in BRAF-mutated cells, acts as a tumor suppressor by regulating multiple cancer-related genes and affects cellular sensitivity to MAPK-related pathway inhibitors, such as BRAF inhibitors, MEK inhibitors, and, or anti-EGFR antibodies." (PMID 35465317, 2022).
cancer (continued). "The ERK (extracellular signal regulated kinase) and mTOR (mammalian target of rapamycin) pathways are recognised key coordinators of the EMT process and cell migration during cancer metastasis, and both pathways can mediate the intracellular signals of OTR and EGFR independently." (PMID 35884900, 2022). "EGFR becomes activated with ligands of the EGF family and is internalized mostly via the clathrin-mediated pathway for triggering uncontrolled proliferation of cancer cells." (PMID 36146510, 2022). "Moreover, anti-EGFR nanobody–drug conjugates possessing two tandemly fused nanobodies (7D12 and 9G8) with MMAE exhibited potent anti-cancer activity in vivo in a solid tumor mouse model." (PMID 36546903, 2022). "In the current study, we presented recent information on the molecular mechanisms of the Bax/Bcl-2 cascade-mediated EGFR pathway in NSCLC and its therapeutic implications along with clinical investigations that facilitate the treatment and management of several cancers, including NSCLC." (PMID 35402265, 2022). "Cytotoxic cells, CD8+ T cells and exhausted CD8+ T cells were lower in EGFR-positive cancer compared to treatment-naïve ALK/EGFR-negative cancer (FC = − 2.2, p = 4.1E-05; FC = − 2.0, p = 0.01 and FC = − 1.7, p = 0.0082)." (PMID 34125345, 2022). "Moreover, it was shown that up-regulation of AQP5 in certain tumors activates EGFR followed by the activation of the ERK1/2 pathway which leads to proliferation and metastasis potential of cancer cells." (PMID 36114463, 2022). "In addition, USP22, EGFR, MET and MAPK were reported to act as targets of miR-30e-5p in human cancers." (PMID 34998399, 2022). "The epidermal growth factor receptor (EGFR) is a transmembrane tyrosine kinase receptor (RTK) and a representative target for cancer therapy to which small molecule tyrosine kinase inhibitors (TKIs) and monoclonal antibodies (mAbs) have been developed, approved, and applied." (PMID 36090901, 2022). "This, in turn, can enable combating widespread strategies used by cancer cells to resist the action of drugs, such as MET amplification or PI3K/AKT activation after targeted EGFR inhibition, PI3K/AKT compensation after mTOR inhibition, or MAPK/STAT3 cross-talk." (PMID 35913978, 2022). "Macrophages educated with either HB-EGF– or AREG-knockdown cancer cells were not able to induce cancer cell invasion in either 4T1 or E0771 cells, indicating that in the cocultures amplified EGFR signaling is required." (PMID 35998057, 2022). "Therefore, using the tyrosine kinase inhibition of EGFR and IGF-1R induces the “BRCAness” and HRD phenotypes in breast and ovarian cancers, leading to PARPi sensitivity in the cancer cells." (PMID 36497275, 2022). "Furthermore, the EGFR/AKT signal pathway participates in promoting proliferation and metastasis of cancer through phosphorylation cascade reaction." (PMID 35237300, 2022). "Vandetanib is the first targeted medication specifically approved by the FDA for the treatment of MTC, acting not only on epidermal growth factor receptor (EGFR), VEGFR, and RET in cancer cells but also inhibiting other TK and serine/threonine kinases and possessing anti-angiogenesis properties." (PMID 36612173, 2022). "However, the infiltration of MDSCs is consistently increased throughout the periods of EGFR-TKI treatment, which can inhibit antitumor immune responses, facilitate cancer progression, and lead to EGFR-TKI resistance." (PMID 35372081, 2022).